SOX11 (SRY-box transcription factor 11)
Diseases named in the same sentence as SOX11 in open-access papers (continued):
Sharing a sentence is not in itself a finding about the gene and the disease.
breast carcinoma (31 papers, 2013 to 2025). "Recently, SOX11 was also implicated as playing a significant role in the mesenchymal state and embryonic cellular phenotypes in breast cancer, possibly conferring tamoxifen resistance." (PMID 37760985, 2023). "In particular, high nuclear expression of SOX11 was found to be associated with longer OS in breast cancer patients, which meant that it was an independent predictor of survival." (PMID 36551589, 2022). "What’s more, patients in the SOX11 altered group had shorter DSS and PFS than patients in the SOX11 unaltered group, suggesting that SOX11 gene alterations, particularly high mRNA levels, were risk factors for prognosis in breast cancer." (PMID 36551589, 2022). "In gastric cancer, astrocytic gliomas and high-grade epithelial ovarian cancers, increased expression of SOX11 is associated with better prognosis, while in breast cancer and cutaneous malignant melanoma, with poor prognosis." (PMID 34996493, 2022). "In breast cancer, high SOX11 expression levels were also significantly associated with distant metastasis and poor prognosis." (PMID 36551589, 2022). "A high level of SOX11 expression is associated with poor overall survival (OS) and increased formation of metastasis in breast cancer patients." (PMID 36551589, 2022). "SOX11 is a key regulator of proliferation and migration of Basal-subtype breast cancer cells, and is associated with poor prognosis." (PMID 33644115, 2021). "High levels of SOX11 are associated with poor overall survival and increased metastasis in breast cancer patients." (PMID 33969421, 2021). "We show that reducing Sox11 levels in the Brca1-deficient mammary tumour (Brca1.3) has similar effects on proliferation, stem cell activity and expression of lineage markers to those observed in studies using embryonic mammary progenitor cells (eG2M5)." (PMID 33969421, 2021). "SOX11 expression in primary breast cancer is associated with increased metastasis formation at distant sites." (PMID 32909943, 2020). "High SOX11 levels in breast tumours are significantly associated with distant metastasis and poor outcome in breast cancer patients." (PMID 32909943, 2020). "Together, these data suggest that patients whose DCIS and primary breast cancers express high levels of SOX11 are among a high-risk metastasis subgroup that should be considered for aggressive therapies in neo-adjuvant settings." (PMID 32909943, 2020). "Sox TFs are also associated with cancer, including SOX11 that shows a 1.5-fold increase in gainability in breast cancer and that has been correlated with breast cancer growth and invasion." (PMID 33077858, 2020). "We have identified a number of genes that are regulated by SOX11 in our mouse models of breast cancer that are also associated with SOX11 expression in both primary breast cancer and breast cancer brain metastasis." (PMID 32909943, 2020). "High‐level SOX11 expression is associated with poor overall survival in all breast cancer patients 9 and a poor outcome in patients with lymph node‐negative disease, a group that normally has a good predicted outcome." (PMID 28707729, 2017). "In breast cancers, one group has recently shown that high grade breast tumors had lower levels of nuclear SOX11 protein, and that nuclear SOX11 was associated with improved clinical outcome." (PMID 26894864, 2016). "Furthermore, SOX11 expression was directly associated with breast cancer stem cell populations and correlated with overexpression of ALDH1." (PMID 36551589, 2022). "When Sox11 levels were reduced in one Brca1-deficient mammary tumour cell line that expressed both epithelial and mesenchymal markers, similar effects on proliferation, stem cell activity and expression of lineage markers to those seen in the embryonic mammary progenitor cells were observed." (PMID 33969421, 2021). "Furthermore, we found that high SOX11 expression is associated with poor breast cancer patient survival." (PMID 26894864, 2016).
breast carcinoma (continued). "Interestingly, SOX11 has been shown to be expressed in a number of malignancies, playing either a diagnostic role, such as in mantle cell lymphomas, pancreatic solid pseudo-papillary tumors, or a prognostic role, such as in brain tumors and breast carcinomas." (PMID 37760985, 2023). "In breast cancer, Sox11 was tied to the induction of EMT and acquisition of a hybrid epithelial/mesenchymal state." (PMID 40393982, 2025). "The necessity for Sox11 for pEMT in a model for intestinal carcinogenesis fits very well with the pro-invasive properties of human SOX11 in head and neck and breast cancer." (PMID 40393982, 2025). "SOX11 has been reported to be downregulated due to epigenetic effects in some breast cancer tumors after treatment with Letrozole; however, SOX11 was found to be upregulated in our analysis." (PMID 39057065, 2024). "SOX11 has recently been shown to behave as an oncogene and is a critical regulator of basal-like and luminal B breast cancers and their metastasis to the brain." (PMID 39057065, 2024). "A similar observation has reportedly been made in breast cancer, in which SOX11 seems to promote an epithelial/mesenchymal hybrid state and alter the tropism of invasive breast cancer cells, also enhancing tamoxifen resistance." (PMID 37760985, 2023). "The TF of SOX11 is a critical regulator of basal-like breast cancer growth, invasion, and basal-like gene expression." (PMID 36077333, 2022). "Another SOX family member SOX11 has also been shown to play significant role during EMT in breast cancer cells." (PMID 34708244, 2022). "It was previously reported that high SOX11 expression was positively correlated with breast cancer tumor size and early tumor grade and negatively correlated with lymph node metastasis in breast cancer." (PMID 36551589, 2022). "Several malignancies, including ovarian cancer and breast cancer, have been correlated to the aberrant upregulation of sox11." (PMID 37255653, 2022). "Next, genetic alterations in SOX11 were analyzed in TCGA-BRCA, where the SOX11 gene was altered in 9% of all breast cancer samples." (PMID 36551589, 2022). "Sox11 is similarly elevated within nuclei at the pushing margins of mouse mammary tumors, and also when present at high levels correlate with increased metastasis and poor overall survival in human breast cancers." (PMID 35302059, 2022). "Our knockdown system in mouse mammary tumour cells shows similar trends in many of the phenotypes we observed when comparing cells expressing higher versus lower levels of SOX11 in human breast cancer models." (PMID 33969421, 2021). "Sox11 levels increase during tumour progression in some mouse models of breast cancer, raising the possibility that Sox11 confers embryonic-like traits to mammary tumour cells and promotes tumour progression." (PMID 33969421, 2021). "We have recently shown that SOX11 confers features of multipotency, impairs differentiation processes and alters tropism of ER− breast cancer cells to metastatic sites." (PMID 33969421, 2021). "Results from our previous studies have suggested that expression of different levels of SOX11 in normal breast and breast cancer cells leads to distinct phenotypes and behaviour of both normal breast stem cells and breast cancer stem cells." (PMID 33969421, 2021). "In the selected key specific DEGs for Basal-subtype breast cancer, the altered expression of SOX11, PLK1, BUB1, OGN, COL4A6, AGTR1, and ADRB2 were significantly correlated with the prognostic survival of the patients." (PMID 33644115, 2021). "We used transplantable mouse mammary tumour lines to study the effect of reducing Sox11 levels on stem cell activity." (PMID 33969421, 2021).
breast carcinoma (continued). "Orthotopic grafting of mammary tumour cells with reduced Sox11 levels led to alterations in tumour-initiating capacity, latency, expression of lineage markers and metastatic burden." (PMID 33969421, 2021). "Together, our results suggest that Sox11 enhances mammary tumour-initiating activity and influences metastatic capacity at specific sites." (PMID 33969421, 2021). "Surprisingly, a dramatic reduction in expression of both fibronectin and epidermal and mammary lineage markers were observed after Sox11 levels were reduced in mammary tumour cells." (PMID 33969421, 2021). "Recent studies have shown that SOX11 messenger RNA (mRNA) is frequently increased in various human cancers, including breast cancer, mantle cell lymphoma, gastrointestinal cancer, epithelial ovarian cancer, and nervous system neoplasms." (PMID 32586027, 2020). "TUBB3, an established SOX11 target, regulates cell growth and invasive potential of ER- breast cancer cells." (PMID 32909943, 2020). "SOX11+ breast cancer cells express markers indicative of phenotypic plasticity and have a high tendency to undergo metastasis." (PMID 32909943, 2020). "We found many SOX11+ breast cancer cell lines express high levels of MEX3A or TUBB3 compared to DCIS.com cell line." (PMID 32909943, 2020). "SOX11 is involved in the processes of several human cancers, including bladder cancer, head and neck cancer and breast cancer." (PMID 32586027, 2020). "SOX11 is highly expressed in brain metastases and is also detected in bone metastasis from breast cancer patients." (PMID 32909943, 2020). "Next, we examined the effect of reducing SOX11 levels in CAL-148 ER- breast cancer cell line that expresses very high SOX11 levels." (PMID 32909943, 2020). "Survival analysis from large sample datasets indicated that SOX11 was closely related to poorer survival in patients with breast cancer." (PMID 32043610, 2020). "SOX11 repression using siRNA reduced both cell migration and invasion in basal-like breast cancer (BLBC) cell lines, supporting a role for SOX11 in promoting breast cancer progression." (PMID 32909943, 2020). "MEX3A, a novel SOX11 downstream effector, regulates cell growth and (E/M) state of ER- breast cancer cells." (PMID 32909943, 2020). "(G) Western blot of MEX3A and TUBB3 in SOX11+ breast cancer cell lines and SOX11- DCIS.com and MCF10A from the MCF10A mammary cell progression series." (PMID 32909943, 2020). "Together, these results are consistent with roles for MEX3A in regulation of cell growth and EMT in SOX11+ ER- breast cancer cells." (PMID 32909943, 2020). "(H) Pie charts representing the percentage of breast cancer samples with a log2 fold-change greater than two in the levels of MEX3A or TUBB3 RNA when SOX11 increased between 0.5- and 2-fold, 2- and 4-fold, or greater than 4-fold in the TCGA dataset." (PMID 32909943, 2020). "SOX11 regulates breast cancer cell proliferation/survival and its over-expression significantly correlates with low survival of breast cancer patients." (PMID 30922366, 2019). "We show that Supervised mode significantly increases statistical power and identifies additional GRNs and associated Master Regulators, such as SOX11 and KLF5 in Basal-like breast cancer." (PMID 30364927, 2019). "Our results showed that high SOX11 expression is correlated with worse clinical outcome in breast cancer patients." (PMID 26894864, 2016). "High SOX11 expression was also found to be an independent prognostic indicator of poor survival in women with breast cancer." (PMID 26894864, 2016). "In a large breast cancer dataset, SOX11 mRNA levels are significantly elevated in each of the intrinsic breast cancer subtypes compared to normal breast samples." (PMID 26894864, 2016). "Our results demonstrating that SOX11 inhibition affected multiple BLBC phenotypes suggest that SOX11 acts as a key signaling molecule in these breast cancers." (PMID 26894864, 2016).
breast carcinoma (continued). "One possibility is that SOX11 is methylated in normal adult mammary cells, and becomes hypomethylated in cancer, particularly Her2-positive and basal-like breast cancers." (PMID 26894864, 2016). "Our results demonstrate that SOX11 is differentially expressed in breast cancer subtypes and is required for the growth of transformed ER-negative breast cancer cells, but not for the growth of ER-positive cancer cells or non-transformed breast cells." (PMID 26894864, 2016). "We also found that high SOX11 expression is an independent prognostic marker of poor survival in women with breast cancer." (PMID 26894864, 2016). "Both BCL11A and SOX11 belong to the top 20 transcriptional regulators that correlate with the core ES signature found activated in aggressive breast cancers." (PMID 23506684, 2013). "Patients with breast cancers expressing higher levels of SOX11 showed worse overall survival than did those with tumors expressing lower levels." (PMID 23506684, 2013). "By using RNA interference to silence SOX11 expression in breast cancer cells, we found evidence that SOX11 regulates breast cancer cell proliferation and cell survival." (PMID 23506684, 2013). "We found that silencing of SOX11 in breast cancer cells led to an increased expression of the apoptotic marker, cleaved caspase-3." (PMID 23506684, 2013). "Expression was also detected in RNA isolated from Brca1-/- mouse mammary tumors: Bcl11a was detected in seven of eight tumors, and Sox11 was detected in two of eight tumors." (PMID 23506684, 2013). "Antibody staining found Sox11 highly expressed at the invasion front in some Brca1-/- mammary tumors." (PMID 23506684, 2013). "It was found that SOX11 was a better biomarker of breast cancer stem cells that could predict cancer recurrence." (PMID 36551589, 2022). "SOX11 promotes breast cancer cell migration and activates SLUG, leading to EMT." (PMID 36033614, 2022). "Another study showed that SOX11 could activate SLUG expression in endocrine-resistant breast cancer cell lines by binding to its promoter, thereby promoting EMT." (PMID 36551589, 2022). "Expression of two potential downstream effectors of SOX11 signalling we recently identified in breast cancers cells, Mex3a and Rcor2, which have links to stem cell proliferation and reprogramming, respectively, were also substantially reduced in Brca1.3 cells with reduced Sox11 levels." (PMID 33969421, 2021). "SOX11 high expression in the Basal-like subtype was associated with poor prognosis (RFS and OS), which was consistent with the prognostic analysis results in all breast cancer." (PMID 33644115, 2021). "Embryonic progenitor cells (eMPC) were used to complement studies of Sox11 in mouse models of breast cancer progression and to examine whether similar functions are regulated in normal mammary progenitor cells compared to tumour progenitor cells." (PMID 33969421, 2021). "Our results show that SOX11 was specifically downregulated in Basal-subtype breast cancer." (PMID 33644115, 2021). "Interestingly, we observed that varying the levels of Sox11 in both the mouse and human mammary tumour cells affects metastatic tropism." (PMID 33969421, 2021). "We propose that lowering Sox11 levels in mouse mammary tumour cells, particularly tumour cells that are in a hybrid epithelial/mesenchymal state, leads to a release from a non-proliferative state with an increased capacity to expand and undergo invasive growth." (PMID 33969421, 2021). "SOX11 upregulation promotes epithelial-to-mesenchymal transition in breast cancer cells." (PMID 32586027, 2020). "Here, we show that SOX11 confers distinct features to ER-negative DCIS.com breast cancer cells, leading to populations enriched with highly plastic hybrid epithelial/mesenchymal cells, which display invasive features and alterations in metastatic tropism when xenografted into mice." (PMID 32909943, 2020).
breast carcinoma (continued). "Triple negative breast cancer (TNBC) cells exhibit robust expression of CD24, suggesting that the inducible model described here mimics what is observed in human TNBC and may present a potential therapeutic opportunity for some SOX11+ breast cancers." (PMID 32909943, 2020). "Finally, we also identify several novel SOX11 targets, many of which are highly correlated with SOX11 expression in primary breast cancers and breast cancer metastases." (PMID 32909943, 2020). "Together, this data suggests it may be necessary to classify SOX11+ tumours, depending on SOX11 expression level, as well as the expression of its effectors in order to stratify breast cancer patients." (PMID 32909943, 2020). "In the inducible model presented here, SOX11 expression confers epithelial/mesenchymal hybrid state, features typical of embryonic mammary cell phenotypes, and influences organ-specific metastatic tropism to breast cancer cells." (PMID 32909943, 2020). "In the present study, we utilized the Gene Expression Omnibus database to identify that SOX11 might exert a pivotal function in conferring tamoxifen resistance of breast cancer." (PMID 32043610, 2020). "As ER status is known to be strongly correlated with breast cancer survival, we used the Curtis dataset, which had the most patients with follow-up survival data, to also examine the correlation of SOX11 with survival among patients after stratifying by ER or HER2 status." (PMID 26894864, 2016). "We next investigated whether SOX11 is a prognostic marker in women with breast cancer by performing survival analyses using multiple available datasets as described in Materials and Methods." (PMID 26894864, 2016). "Several potential mechanisms may be responsible for the elevated SOX11 expression in breast cancer compared to normal breast tissue." (PMID 26894864, 2016). "In breast cancer patients, methylation of the SOX11 promoter was shown to correlate with estrogen receptor status, suggesting that SOX11 may be functionally re-expressed during treatment with HDAC inhibitors in specific patient subgroups." (PMID 25880212, 2015). "Finally, we demonstrate a correlation between SOX11 methylation, expression and subtypes in primary breast cancers." (PMID 25880212, 2015). "Furthermore, in breast cancer, we demonstrate a correlation between SOX11 methylation and clinical subtype." (PMID 25880212, 2015). "Four transcription factors (Bcl11a, Grhl3, Prox1, Sox11) activated in Brca1-/- mouse tumors and basal-like human breast cancers across multiple datasets were chosen for validation studies, and all were confirmed to be embryonic-enriched and highly expressed by some tumors." (PMID 23506684, 2013). "High levels of SOX11 expression are associated with poor overall survival in breast cancer patients, but its function in breast epithelial cells is not clear and remains to be further investigated." (PMID 23506684, 2013). "According to a recent study, SOX4 and SOX11 could promote breast cancer metastasis." (PMID 39741182, 2025). "We also investigated the effect of reducing Sox11 levels in two transplantable Brca1-deficient oestrogen receptor-negative mouse mammary tumour cell lines, to assess whether Sox11 regulates similar functions in tumour progenitor cells." (PMID 33969421, 2021). "Hence, targeting SOX11 could be a potential therapeutic strategy to tackle tamoxifen resistance in breast cancer." (PMID 32043610, 2020). "Interestingly, SOX11 methylation correlates to ER positivity in breast cancer patients." (PMID 25880212, 2015). "We found that silencing of SOX11 in breast cancer cells reduces cell survival and cell viability, and SOX11 overexpression leads to increased proliferation rates, suggesting that SOX11 could have a similar function in regulation of proliferation and survival in several types of cells." (PMID 23506684, 2013).